MYF6 (myogenic factor 6)
Description:
Involved in muscle differentiation (myogenic factor). Induces fibroblasts to differentiate into myoblasts. Probable sequence specific DNA-binding protein.
Synonyms: Myf-6; bHLHc4; MRF4; CNM3
Tractability: No criterion of Open Targets' tractability assessment is met for any kind of drug.
Gene: Protein-coding gene on chromosome 12 (80,707,633 to 80,709,557, forward strand). Ensembl gene ENSG00000111046.
Subcellular location: Nucleus
Subcellular location (Human Protein Atlas): Nucleoplasm; Cytosol; Mitotic spindle
Pathways (Reactome):
Developmental Biology: Myogenesis
Signal Transduction: TGFBR3 expression
Gene Ontology:
Molecular function: protein binding; sequence-specific double-stranded DNA binding; DNA-binding transcription factor activity; DNA-binding transcription factor activity, RNA polymerase II-specific; E-box binding; RNA polymerase II cis-regulatory region sequence-specific DNA binding; DNA-binding transcription activator activity, RNA polymerase II-specific; protein dimerization activity
Biological process: muscle cell fate commitment; positive regulation of myoblast differentiation; positive regulation of skeletal muscle fiber development; positive regulation of transcription by RNA polymerase II; regulation of transcription by RNA polymerase II; skeletal muscle cell differentiation; skeletal muscle tissue development; animal organ development; muscle organ development; regulation of DNA-templated transcription; skeletal muscle tissue regeneration; tissue development
Cellular component: nucleoplasm; chromatin; nucleus; RNA polymerase II transcription regulator complex
Genetic constraint (gnomAD): Loss-of-function variants: 20 observed, 23.44 expected, observed/expected ratio (o/e) 0.85, 90% interval 0.6 to 1.24. The upper end of that interval is the gene's LOEUF score, 1.24, which puts it in group 5 of 6, group 1 being the genes least tolerant of losing a copy. Missense variants: 320 observed, 325.37 expected, observed/expected ratio (o/e) 0.98, 90% interval 0.9 to 1.08. Synonymous variants: 124 observed, 134.77 expected, observed/expected ratio (o/e) 0.92, 90% interval 0.79 to 1.07.
Homologues: Orthologues: chimpanzee MYF6 (100% identical), macaque MYF6 (100% identical), rabbit MYF6 (98% identical), guinea pig MYF6 (97% identical), pig MYF6 (97% identical), dog MYF6 (96% identical), mouse Myf6 (95% identical), rat Myf6 (95% identical), tropical clawed frog myf6 (73% identical), zebrafish myf6 (62% identical), Drosophila melanogaster nau (38% identical), Caenorhabditis elegans hlh-1 (33% identical). Paralogues in human: MYOG (43% identical), MYF5 (41% identical), MYOD1 (38% identical).
Diseases named in the same sentence as MYF6 in open-access papers:
MYF6 is named in the same sentence as 34 diseases in open-access papers, as found by Europe PMC text mining. Sharing a sentence is not in itself a finding about the gene and the disease. The quoted sentences say what the papers report.
rhabdomyosarcoma (4 papers, 1991 to 2020). A rare aggressive malignant mesenchymal neoplasm arising from skeletal muscle. "MYF6 expression has been reported for a narrow group of solid tumors including of rhabdomyosarcoma and corticotroph macroadenomas." (PMID 32040482, 2020). "In neoplasia, MYF6 expression was reported in 33% of rhabdomyosarcomas and silent corticotroph macroadenomas." (PMID 32040482, 2020). "When PAX3:FKHR expression was targeted by the Myf6 promoter in terminally differentiating skeletal muscle, mice developed alveaolar rhabdomyosarcoma with a very low penetrance (< 1%)." (PMID 27191748, 2017). "In order to generate a more robust alveolar rhabdomyosarcoma model, mice specifically expressing a Pax3-Fkhr transgene in the muscle under the influence of Myf6-Cre-mediated activation were generated." (PMID 23036318, 2012). "Northern analysis of tumour RNA has been used to examine the expression of members of the myf family of muscle determining genes (myf3, myf4, myf5 and myf6) in a series of 20 rhabdomyosarcomas." (PMID 1764365, 1991).
lung disease (2 papers, 2013 to 2018). "In this study, among the 7 genes which demonstrated hypermethylation in stage I NSCLC compared with non-cancerous lung diseases, 5 genes (MYF6, SIX6, PHOX2A, FOLX2 and SOX1) were found for the first time to be abonormally methylated in NSCLC." (PMID 23599765, 2013). "In addition, the methylation frequency of MYF6 in stage I non-small cell lung cancer is obviously higher than that of non-cancerous lung disease control, which suggested that MYF6 could offer a specificity and a sensitivity in the stage I non-small cell lung cancer diagnosis." (PMID 29933410, 2018). "The methylation frequencies (29.70–64.36%) of 7 genes (MYF6, SIX6, SOX1, RARB, BCL2, PHOX2A and FOLX2) in stage I NSCLC were significantly higher compared with those in non-cancerous lung disease controls (P<0.05)." (PMID 23599765, 2013). "The methyaltion frequencies of 7 genes: MYF6, SIX6, SOX1, RARB, BCL2, PHOX2A and FOLX2 were significantly higher in stage I NSCLC than in non-cancerous lung diseases." (PMID 23599765, 2013). "A panel of 4 genes (MYF6, SIX6, BCL2 and RARB) was able to diagnose stage I NSCLC from non-cancerous lung diseases with a sensitivity of 93.07% and a specificity of 86.67%." (PMID 23599765, 2013). "This study showed that 7 genes (MYF6, SIX6, SOX1, RARB, BCL2, PHOX2A and FOLX2) were frequently methylated in 101 cases of patients with stage I NSCLC, while rarely methylated in 30 patients with non-cancerous lung diseases." (PMID 23599765, 2013).
congenital adrenal hyperplasia (1 paper, 2022). Congenital adrenal hyperplasia (CAH) is an inherited endocrine disorder caused by a steroidogenic enzyme deficiency that is characterized by adrenal insufficiency and variable degrees of hyper or hypo androgyny manifestations, depending of the type and the severity of the disease. "Upregulation of genes associated with other diseases, renal dysfunction or cancer was also observed, such as Fras1 (Fraser syndrome 1), Cyp21a1 (congenital adrenal hyperplasia), Dbh (associated with kidney dysfunction), and Akr1c1/Myt1/Myf6/Scg2 (kidney cancer)." (PMID 36130284, 2022).
hepatocellular carcinoma (1 paper, 2018). A malignant tumor that arises from hepatocytes. "It is found that the MYF6 is a differentially methylation gene in plasma cf-DNA in the different stage of hepatocellular carcinoma development." (PMID 29933410, 2018).
leukemia (1 paper, 2020). A malignant (clonal) hematologic disorder, involving hematopoietic stem cells and characterized by the presence of primitive or atypical myeloid or lymphoid cells in the bone marrow and the blood. "MYF6 protein could be detected in the nuclear fraction of MYF6+ HCL and CLL cells, and in these leukemias, MYF6 PQ-PCR could be used for MRD detection with sensitivities of 1/105 and 2/105, respectively." (PMID 32040482, 2020). "MYF6, universally expressed in HCL and in most CLL samples, may be a useful biomarker for these leukemias." (PMID 32040482, 2020).
mantle cell lymphoma (1 paper, 2020). Mantle cell lymphoma is a rare form of malignant non-Hodgkin lymphoma affecting B lymphocytes in the lymph nodes in a region called the ``mantle zone''. "Rates of MYF6 expression were lower for other hematologic malignancies, including 92% for IGHV4-34+ HCL, 32% for IGHV4-34-negative HCLv, 41% for IGHV4-34+ HCLv, 73% for CLL, 60% for marginal zone lymphoma (MZL) and 8% for mantle cell lymphoma (MCL)." (PMID 32040482, 2020). "MYF6-expression was also detected in 18 (35%) of 51 with HCLv, 11 (92%) of 12 with HCL expressing unmutated IGHV4-34, 35 (73%) of 48 with chronic lymphocytic leukemia (CLL), and 1 (8%) of 12 with mantle cell lymphoma." (PMID 32040482, 2020).
synovial sarcoma (1 paper, 2024). "Cre/LoxP-driven mouse synovial sarcoma (SS) most readily forms in a Myf5-expressing skeletal muscle-specific lineage, whereas fusion oncogene expression in early myogenic precursors (Pax3/Pax7) was fatal and myofiber expression (Myf6) caused myopathy." (PMID 38916046, 2024).
tumor (13 papers, 1991 to 2025). "Based on their genotypes, we identified n = 23 tumours corresponding to the ML cluster (Pax3::Foxo1 in Myf5, Myf6, or Pax3 lineage) and n = 33 tumours corresponding to the MR cluster (other mutations in any lineage or Pax3::Foxo1 in Pax7 lineage)." (PMID 39812007, 2025). "We found that Myf6 lineage tumours were more prevalent in the ML cluster (7/11, 63.6%) than in the MR cluster (4/20, 20%) (p = 0.023)." (PMID 39812007, 2025). "The findings indicated that MYF6 exhibited higher expression levels in the normal group compared to the tumor group, whereas the remaining genes exhibited elevated expression levels in the tumor group in relation to the normal group." (PMID 37926766, 2023). "Future studies will address the salivary cell subtypes belonging to the Pax7, Myf5, and Myf6 lineages, timing of tumor initiation, and the potential stem-cell like plasticity of this ontogeny." (PMID 25883905, 2015). "Transcription of myf6 occurred in 28% of tumours, but there were several transcript sizes (1.2, 1.5, 2.0 and 3.5 kb) and in some individual tumours two or more transcripts were observed." (PMID 1764365, 1991). "Initial examination of these clusters/subsets revealed that all GEMM tumours in ML clusters corresponded to Pax3::Foxo1 in one of three lineages (Myf5, Myf6, and Pax3) while all tumours in MR1 corresponded to DNA alterations other than Pax3::Foxo1 in these same three lineages." (PMID 39812007, 2025). "Finally, tumours in MR2 corresponded to either Pax3::Foxo1 in the Pax7 lineage or DNA alterations other than Pax3::Foxo1 in one of three lineages (Myf6, Pax3, or Pax7)." (PMID 39812007, 2025). "Overall, moderate agreement (κ = 0.44, 95% CI: 0.11–0.77) was demonstrated between the presence of Myf6 lineage and high Pax3::Foxo1 expression, implicating an interaction between Myf6 lineage and Pax3::Foxo1 during the development of these FP RMS tumours." (PMID 39812007, 2025). "Both TCP and Myf6-Cre;Cdkn2aFlox/Flox;Pax3P3Fm/P3Fm (MCP) mutant mice developed tumors with a median tumor-free survival of 146 days and 138 days, respectively." (PMID 37968277, 2023). "The results of DNA samples from 40 cancer and 25 normal lung tissues showed a good diagnostic potential of selected RCGY sites in regulatory regions of MYF6, SIX6, RXRG, LHX1, RASSF1A and TERT genes with relatively high sensitivity (80.0 %) and specificity (88.0 %) of LC detection in tumor DNA." (PMID 31526458, 2019).
cancer (7 papers, 2012 to 2022). A tumor composed of atypical neoplastic, often pleomorphic cells that invade other tissues. "Thus it can be seen that MYF6 methylation was associated with the development of cancer." (PMID 29933410, 2018). "The methylation of 4 genes, MYF6, SIX6, PHOX2A, FOLX2, has never previously been reported in any types of cancer." (PMID 23599765, 2013).
myopathy (3 papers, 2017 to 2025). A disease of the muscle in which the muscle fibers do not function properly. "Interestingly, the induction of SYT-SSX expression through Hprt-Cre, Pax3-Cre, or Pax7-Cre resulted in embryonic lethality, and SYT-SSX expression in Myf6-expressing myocytes or Myf6-expressing myofibers resulted in myopathy but no tumors." (PMID 27191748, 2017).
hematologic malignancies (1 paper, 2020). "We found that 100% of 154 HCL samples were positive for MYF6 by RQ-PCR, with less percentages of other hematologic malignancies positive." (PMID 32040482, 2020). "Thus, MYF6 was positive by RQ-PCR in all patients with HCL, in most patients with CLL, MZL, and VH4-34+ HCL, and in a minority of patients with other hematologic malignancies or normal controls, including HCLv." (PMID 32040482, 2020).
MYF6 also shares sentences with these, for which no sentence is quoted: Obesity (2 papers); sarcopenia (2); adult T-cell leukemia (1); Arrhythmia (1); atherosclerosis (1); Atrophy (1); Burkitt lymphoma (1); diffuse large B-cell lymphoma (1); Duchenne muscular dystrophy (1); follicular lymphoma (1); hairy cell leukemia (1); Hodgkins lymphoma (1); hypogonadism (1); infection (1); kidney cancer (1); malnutrition (1); marginal zone lymphoma (1); muscle atrophy (1); myotubular myopathy (1); non-small cell lung carcinoma (1); plasma cell leukemia (1); primary effusion lymphoma (1); skeletal muscle disorder (1).